DPP4 (dipeptidyl peptidase 4)
Diseases named in the same sentence as DPP4 in open-access papers (continued):
Sharing a sentence is not in itself a finding about the gene and the disease.
diabetes (continued). "A total of 1 161 254 adults with type 2 diabetes mellitus initiating therapy with low‐affinity cardiac mitoKATP channel sulfonylureas, high‐affinity sulfonylureas, and DPP‐4 inhibitors were identified." (PMID 41017568, 2025). "A meta-analysis of the efficacy of recently introduced diabetes therapies showed the average reduction in HbA1c in response to DPP4 inhibitors, SGLT2 is, and GLP1-RA was 0.53%, 0.79%, and 0.78% respectively." (PMID 40993285, 2025). "DPP4 plays a multifaceted role, influencing not only diabetes and glucose metabolism but also affecting cardiovascular health and potentially contributing to heart diseases such as atherosclerosis." (PMID 40249657, 2025). "DPP4 inhibitors, also known as gliptins, are used in the treatment of type 2 diabetes mellitus to improve glucose homeostasis." (PMID 40490517, 2025). "Our findings reveal that DPP4 inhibitors effectively limit the progression of diabetes-related cognitive disorders." (PMID 38860903, 2025). "DPP4 plays a role in immunity, cancer, and diabetes, but also antagonizes vasoconstriction and platelet aggregation via cleavage of NPY1-36, a neuropeptide that can be found in endothelial cells." (PMID 41159750, 2025). "Since NPY cannot yet be routinely administered to patients, we investigated the effects of sitagliptin, a dipeptidyl peptidase-4 (DPP4) inhibitor approved for the treatment of type 2 diabetes mellitus, on social fear and comorbid depression in mice." (PMID 40490517, 2025). "Prescribed diabetes medications included the following: metformin, 57.5% (n=417); insulin, 14.9% (n=108); secretagogues, 11.3% (n=82); DPP-4 inhibitors, 8.3% (n=60); sodium–glucose cotransporter-2 inhibitors, 7.9% (n=57); and GLP-1 inhibitors, 5.0% (n=36)." (PMID 40044453, 2025). "Serine protease Dipeptidyl peptidase-4 (DPP4) is an important therapeutic target for managing diabetes since it is essential to metabolising insulin and glucose." (PMID 40063647, 2025). "DPP4 has been shown to be significantly upregulated in various proinflammatory conditions including obesity, diabetes, thrombosis, and atherosclerotic vascular diseases." (PMID 40742315, 2025). "Once-weekly trelagliptin is a novel, orally active, highly selective DPP-4 inhibitor that has been approved for use in type 2 diabetes mellitus in Japan." (PMID 40605903, 2025). "Dipeptidyl peptidase 4 inhibitors (DPP4is) are considered safe for use in patients with diabetes mellitus and kidney dysfunction." (PMID 39927258, 2025). "DPP-4 inhibitors, such as Sitagliptin, Saxagliptin, and Linagliptin, have been used since 2006 and are widely prescribed for managing type 2 diabetes mellitus." (PMID 40725973, 2025). "Vildagliptin, a dipeptidyl peptidase-4 inhibitor (DPP-4i) used in the treatment of type 2 diabetes mellitus (DM2), stands out for its safety in older adults." (PMID 40498942, 2025). "It has been demonstrated previously that DPP4 is regulated by various stimuli, such as smoking, diabetes, and inflammation." (PMID 40048293, 2025). "In the context of DPP4 inhibition and diabetes research, QSAR models provide insight into the structural requirements for inhibitory potency and selectivity, supporting the discovery of novel antidiabetic agents." (PMID 40565043, 2025). "Diabetes medications included insulin (39.1%) and oral hypoglycaemic agents [sulfonylureas (n = 189; 23.6%), dipeptidyl peptidase-4 inhibitors (n = 249; 31.1%) and metformin (n = 481; 60.0%)]." (PMID 39916475, 2025). "Adults with diabetes hospitalized for confirmed COVID-19 between 1 March 2021, and 28 February 2022, were included and stratified by DPP-4 inhibitor use." (PMID 40869643, 2025). "The clinical implications of our findings are particularly significant given that DPP4 inhibitors are already FDA-approved for diabetes management." (PMID 40766751, 2025).
diabetes (continued). "Val-boroPro, also known as PT-100, Talabostat and BXCL701, was initially synthesised as a DPP4 inhibitor for diabetes therapy but was then found to also inhibit DPP8 and DPP9 substantively." (PMID 40293537, 2025). "Dipeptidyl Peptidase-4 (DPP-4) is an FDA-approved target for the treatment of type 2 diabetes mellitus (T2DM)." (PMID 40761758, 2025). "In conclusion, the pleiotropic effects, favorable safety profile, and suitability for vulnerable populations position DPP-4 inhibitors as promising agents in the management of cardio-cerebrovascular complications in diabetes." (PMID 40771927, 2025). "Dipeptidyl peptidase‐4 (DPP‐4) is one of the known targets for diabetes as it increases the blood glucose level after consuming food." (PMID 39865621, 2025). "While DPP4 inhibitors are clinically deployed for diabetes, our data expand their therapeutic relevance to CD-related intestinal stricture, a concept supported by preclinical studies in scleroderma, diabetic nephropathy, pulmonary and hepatic fibrosis." (PMID 41334589, 2025). "The two groups differed significantly for sex, diabetes duration, baseline BMI, HbA1c, lipids, prevalence of macroangiopathy, comorbidity index and therapy with DPP-4 inhibitors, statins and anti-platelet agents." (PMID 40119903, 2025). "But the enzyme dipeptidyl peptidase 4 (DPP‐4) inactivates GLP‐1, whose impaired secretion is linked to diabetes." (PMID 40650469, 2025). "Other diabetes treatments included liraglutide (26%), dipeptidyl peptidase-4 inhibitors (15%), sulfonylurea (18%), sodium-glucose transport inhibitor (SGLT2i) (9%), and insulin (39%)." (PMID 40155929, 2025). "Recent success with the use of glucagon-like peptide-1 (GLP-1) receptor analogs and dipeptidyl peptidase-4 inhibitors for the treatment of patients with diabetes has highlighted the role of the intestine as an endocrine organ." (PMID 39826690, 2025). "Transitioning to a once-weekly dipeptidyl peptidase (DPP)-4 inhibitor has been shown to be both effective and well tolerated in diabetes management, resulting in improved patient compliance, satisfaction, and quality of life." (PMID 40605903, 2025). "Our findings align with previous observational studies suggesting a potential protective role of DPP-4 inhibitors in patients with type 2 diabetes mellitus and COVID-19, particularly among those receiving insulin therapy." (PMID 40869643, 2025). "Dipeptidyl peptidase-4 (DPP-4) inhibitors are widely used for the treatment of type 2 diabetes mellitus." (PMID 40895902, 2025). "Trelagliptin and vildagliptin are oral dipeptidyl peptidase-4 (DPP-4) inhibitors used in the treatment of type 2 diabetes mellitus." (PMID 40605903, 2025). "For example, adapalene is an acne medication, and saxagliptin is a dipeptidyl peptidase-4 (DPP-4) inhibitor used in the treatment of diabetes mellitus." (PMID 41154833, 2025). "Dipeptidyl peptidase 4 inhibitors (DPP-4 inhibitors) are used as second-line drugs in the treatment of type 2 diabetes mellitus (T2DM) patients." (PMID 40901275, 2025). "Sitagliptin, a dipeptidyl peptidase-4 (DPP-4) inhibitor, has demonstrated efficacy in the management of type 2 diabetes mellitus (T2DM)." (PMID 41048511, 2025). "Recent evidence shows that dipeptidyl peptidase-4 inhibitors (DPP4i), used in diabetes management, can induce BP (DPP4i-BP)." (PMID 40749047, 2025). "DPP4 inhibitors are commonly used in diabetes treatment, but their effects on other conditions, such as cardiovascular disorders and inflammatory diseases, are also under investigation." (PMID 41463358, 2025). "NHE3 activity is related to DPP4 with which it forms complex, while increased expression of the exchanger is related to diabetes and heart failure." (PMID 39861115, 2025). "Incretin mimetics known as glucagon-like peptide-1 (GLP-1) agonists and dipeptidyl peptidase-4 (DPP-4) inhibitors, both used in diabetes treatment, have been associated with the upregulation of SIRT1." (PMID 39861104, 2025).
diabetes (continued). "Incretin hormone-targeting dipeptidyl peptidase-4 (DPP-4) inhibitors are an important class of agents indicated for the management of type 2 diabetes mellitus T2DM that owe their significant glucose-lowering effect to up-regulated endogenous incretin levels." (PMID 39860434, 2025). "A multivariate analysis was conducted to evaluate the relationship between selected comorbidities and their associated medications, specifically hypertension (ACEi and ARBs), diabetes (biguanides and DPP4 inhibitors), and metabolic disorders (statins)." (PMID 40720062, 2025). "In regression models, a significant interaction was found between continuous glucose monitoring (CGM) use and use of 3 anti‐diabetes medication classes: sulfonylureas, DPP‐4 inhibitors and GLP‐1 RAs." (PMID 40851538, 2025). "The Saxagliptin Assessment of Vascular Outcomes Recorded in Patients with Diabetes Mellitus-Thrombolysis in Myocardial Infarction (SAVOR-TIMI) trial was among the first completed studies evaluating DPP-4 inhibitors." (PMID 40093018, 2025). "Keywords such as “T2DM,” "Type 2 Diabetes Mellitus," “SGLT2i,” "Sodium-glucose cotransporter-2 inhibitors," “DPP-4 inhibitors,” “Biguanides,” “Metformin,” and “GLP-1 RA” were utilized to identify recent and relevant findings." (PMID 40741551, 2025). "Beyond their glucose-lowering effects, DPP-4 inhibitors have been implicated in processes relevant to both atherosclerosis and CAVS, particularly in individuals with type 2 diabetes mellitus, a population prone to overlapping vascular and valvular pathologies." (PMID 40943088, 2025). "Cochrane, Embase, and PubMed databases, which compared the use of DPP-4 inhibitors and reported cardiovascular outcomes and heart failure events in patients with type 2 diabetes mellitus (T2DM), were searched using specific terms." (PMID 40832578, 2025). "Injection of IL-10-treated SVFs into the adipose tissue decreased diabetes-induced gluconeogenesis gene expression, DPP4 activity, and insulin resistance by enhancing Treg cells in diabetic mice." (PMID 39125659, 2024). "It has been previously shown that topical delivery of the dipeptidyl peptidase-4 (DPP-4) inhibitor sitagliptin can protect against diabetes-mediated dysfunction of the retinal NVU in the db/db mouse." (PMID 39616390, 2024). "Despite the advantages of DPP-4 inhibitors in managing diabetes in patients with renal impairment, there are some limitations and considerations to keep in mind." (PMID 39768866, 2024). "The most common diabetes drugs were Biguanides (Metformin), DPP-4 inhibitors, GLP-1 agonists, Insulin, SGLT-2 inhibitors, and Sulfonylurea." (PMID 39759947, 2024). "DPP4, a serine protease primarily expressed in liver tissues, exhibits significant involvement in conditions like obesity, diabetes, and cancer." (PMID 38424257, 2024). "Dipeptidyl peptidase-4 inhibitors (DPP-4i) served as oral antidiabetic agents for treatment of type 2 diabetes mellitus (T2DM)." (PMID 38997754, 2024). "A total of 39 patients with type-2 diabetes mellitus (T2DM) treated with the combination of DPP4 and SGLT2 inhibitors were included in this multicenter pilot study." (PMID 39114607, 2024). "Rats with streptozotocin-induced diabetes were treated with the DPP-4 inhibitor sitagliptin (10 mg/kg/day for 6 weeks)." (PMID 38732142, 2024). "Recent preclinical studies in mouse models of diabetes have reported the beneficial effects of certain antidiabetic drugs, such as dipeptidyl peptidase-4 (DPP-4) inhibitors and metformin, on neuroinflammation and cognitive impairment." (PMID 38334676, 2024). "As research continues to advance our understanding of diabetes management in the context of renal impairment, DPP-4 inhibitors will likely remain a cornerstone of therapy, providing both glycemic control and potential renal protection." (PMID 39768866, 2024).
diabetes (continued). "DPP-4 inhibitors are used to treat patients with type 2 diabetes mellitus in order to extend the half-life of incretins, as active incretins cause pancreatic β cells to secrete insulin." (PMID 38337597, 2024). "Use of sulfonylureas and insulin carries a greater risk of hypoglycemia than diabetes medications acting via alternative mechanisms, including GLP-1 RAs such as liraglutide and DPP4 inhibitors such as sitagliptin." (PMID 39546502, 2024). "The variability across DPP-4 inhibitors highlights the need for individualized treatment strategies in heart failure patients with diabetes." (PMID 39768866, 2024). "The analysis demonstrated that diabetes is an independent contributing factor for DPP4 activity (unstandardized β=63.5, 95% CI 28.7-98.4, p=0.011), while other parameters are not." (PMID 39507187, 2024). "The leucocyte membrane protein CD26/DPP-4 enzyme is the target of the gliptin family of drugs for the treatment of diabetes and metabolic disorders." (PMID 39201726, 2024). "The data showed that DPP4 inhibitors significantly reduced the incidence rate of cognitive impairment in type 2 diabetes mellitus (SMD: 0.99; 95% CI [0.59, 1.38])." (PMID 38379936, 2024). "The beneficial effects of DPP-4 inhibitors on cognition function were also observed in people suffering from diabetes mellitus type 2 and Alzheimer’s disease." (PMID 38474255, 2024). "This review critically examines current evidence on the use of DPP-4 inhibitors in patients with coexisting diabetes and heart failure, focusing on pharmacodynamics, safety, and efficacy outcomes." (PMID 39768866, 2024). "DPP-4 inhibitors, also known as “gliptins,” are relatively new drugs used in the treatment of diabetes mellitus." (PMID 38510866, 2024). "Currently, drugs affecting DPP-4 inhibitors have been approved for use in the treatment of type 2 diabetes mellitus." (PMID 38474255, 2024). "DPP-4 inhibitors or gliptins are currently approved as anti-hyperglycaemic agents for type 2 diabetes mellitus, with well-proven efficacy and safety." (PMID 39526061, 2024). "We demonstrate that qPISA can direct protein engineering efforts like the stabilization of GLP-1, a key DPP4 substrate used in the treatment of diabetes and obesity." (PMID 39468329, 2024). "Both GIP and GLP1 are susceptible to degradation by the enzyme dipeptidyl peptidase 4 (DPP-4), which has prompted the development of DPP-4 inhibitors as a treatment for type 2 diabetes mellitus." (PMID 38398492, 2024). "Although all these alkaloids have the ability to inhibit DPP-4, their differing chemical structures and binding characteristics suggest a potential synergistic role in diabetes treatment." (PMID 38792165, 2024). "Dipeptidyl peptidase-4 (DPP-4) inhibition has beneficial effects on various metabolic indicators in diabetes." (PMID 39271520, 2024). "Data showed that DPP-4 inhibitors were much more prescribed in diabetes centers than in general hospitals, while around 62% of patients with ASCVD are not taking Metformin." (PMID 39759947, 2024). "In our previous study, we identified a notable increase in miR-548ag content after obesity, which contributes to the progression of Type 2 diabetes Mellitus(T2DM) through the up-regulation of Dipeptidyl Peptidase-4(DPP4) expression within the liver." (PMID 38424257, 2024). "To investigate why DPP-4 and Angptl4 levels were elevated in diabetes, we performed miRNA array analysis in control and diabetic mice." (PMID 39630889, 2024). "DPP-4 inhibitors were administered to patients with diabetes mellitus complicated by DM1, and the CGM results were compared." (PMID 39274465, 2024). "Dipeptidyl peptidase-4 (DPP-4) inhibitors are a class of drugs that enhance the incretin-insulin pathway and offer effective glycemic control in type 2 diabetes mellitus." (PMID 38523307, 2024).
diabetes (continued). "DPP4 inhibitors significantly improved type 2 diabetic mellitus individuals' cognitive impairment and reduced fasting blood glucose, 2-hour postprandial blood glucose, and glycosylated hemoglobin." (PMID 38379936, 2024). "The peptidase activity of CD26/DPP4 affects multiple proteins, including incretin hormones and has led to the development of CD26/DPP4 inhibitors as therapeutic agents against diabetes." (PMID 39684311, 2024). "Sitagliptin is, therefore, considered a safer choice among DPP-4 inhibitors for patients with concurrent diabetes and heart failure." (PMID 39768866, 2024). "Further research is needed to explore the role and mechanism of DPP-4 in the progression and remission of diabetes." (PMID 38476668, 2024). "We can achieve it using both relatively new drugs like the phlazines or the still-investigational DPP4 inhibitors, but the long-known diabetes drugs like insulin or metformin will work just as well here." (PMID 38672121, 2024). "We analyzed individuals with diabetes who were newly prescribed SGLT2i or dipeptidyl peptidase 4 inhibitors (DPP4i) in a large-scale epidemiological database." (PMID 38600275, 2024). "Sodium-glucose cotransporter 2 inhibitors (SGLT2i) and dipeptidyl peptidase-4 inhibitors (DPP4i) are important second-line treatments for patients with type 2 diabetes mellitus (T2DM)." (PMID 39139635, 2024). "DPP-4 inhibitors are used to treat patients with type 2 diabetes mellitus in order to extend the half-life of incretins." (PMID 38337597, 2024). "DPP-4 inhibitors have distinct advantages in the management of diabetes in patients with impaired renal function." (PMID 39768866, 2024). "Any diabetes medicine taken by the patients can be categorized into the following nine categories: Metformin, Sulfonylurea, Pioglitazone, DPP-4- Inhibitor, GLP-1-RA, SGLT2-Inhibitor, Basal Insulin, Prandial Insulin, and Mixed Insulin." (PMID 38617952, 2024). "Beyond diabetes, DPP-4 has also been identified as a moonlighting protein involved in the early stages of cancer development." (PMID 40066124, 2024). "A COX-2/iPGE2/DPP-4 cascade was verified to also have a relevant role in the proximal tubular damage in septic patients with diabetes." (PMID 39656542, 2024). "Despite the emergence of newer agents like sodium-glucose cotransporter-2 (SGLT2) inhibitors and GLP-1 receptor agonists, DPP-4 inhibitors have a significant role in diabetes management." (PMID 39737272, 2024). "While DPP-4 inhibitors remain a viable option in diabetes management, caution is warranted in patients with advanced heart failure, and future research is essential to refine patient-specific guidelines." (PMID 39768866, 2024). "The diabetes and hypertension were well controlled with medications such as dipeptidyl peptidase-4 inhibitors and sodium-glucose transport protein 2 inhibitors for diabetes and angiotensin II receptor and calcium channel blockers for hypertension." (PMID 39202049, 2024). "DPP-4 inhibitors, which work by suppressing incretin function, are promising agents for treating diabetes with fewer adverse effects." (PMID 40066124, 2024). "One-fifth of patients were treated for diabetes mellitus, chiefly with insulin, DPP-4 inhibitors, metformin, and glinides." (PMID 38999282, 2024). "Another recent study showed that CRC patients with diabetes mellitus treated with DPP4 inhibitors showed significantly better 5-year disease-free survival compared to metformin-treated counterparts." (PMID 39200895, 2024). "Dipeptidyl peptidase-4 (DPP-4) is an important target for the clinical treatment of several diseases including diabetes, obesity, cardiovascular diseases, and non-alcoholic fatty liver disease (NAFLD)." (PMID 38792165, 2024). "The enzymatic activity of CD26/DPP4, such as degradation and inactivation of incretins, has been the focus of many studies, and DPP4 inhibitors have been used clinically for the treatment of diabetes mellitus." (PMID 38255821, 2024).